RNU6-527P (RNA, U6 small nuclear 527, pseudogene)
Gene: Small nuclear RNA gene on chromosome 6 (106,607,716 to 106,607,819, forward strand). Ensembl gene ENSG00000200295.
Homologues: Orthologues: chimpanzee U6 (98% identical), macaque U6 (92% identical), guinea pig U6 (87% identical), rat LOC120098750 (85% identical), mouse Gm25141 (83% identical), pig U6 (82% identical), rat LOC120101188 (80% identical), rat LOC120101192 (78% identical), dog U6 (75% identical). Paralogues in human: RNU6-97P (88% identical), RNU6-1091P (87% identical), RNU6-1094P (87% identical), RNU6-175P (87% identical), RNU6-24P (87% identical), RNU6-43P (87% identical), RNU6-454P (87% identical), RNU6-11P (86% identical), RNU6-16P (86% identical), RNU6-379P (86% identical), RNU6-37P (86% identical), RNU6-637P (86% identical), and 1288 more.